TNFSF14 (TNF superfamily member 14)
Diseases named in the same sentence as TNFSF14 in open-access papers (continued):
Sharing a sentence is not in itself a finding about the gene and the disease.
renal fibrosis (4 papers, 2020 to 2024). A final common manifestation of a wide variety of chronic kidney diseases characterized by glomerulosclerosis and tubulointerstitial fibrosis. "To explore the association of pro-fibrotic factor Sphk1 with TNFSF14 pathway during renal fibrosis pathogenesis, we measured Sphk1 expression in Tnfsf14-deficient mice." (PMID 33231567, 2020). "Accordingly, Tnfsf14 deficiency led to a marked reduction in renal fibrosis lesions and inflammatory cytokines expression in the UUO mice." (PMID 33231567, 2020). "Moreover, this is the first report showing that the TNFSF14 pathway potentiates pro-fibrotic factor Sphk1 expression, which may be the underlying mechanism of TNFSF14-mediated renal fibrosis." (PMID 33231567, 2020). "In the present study, we have provided direct evidence, for the first time, that TNFSF14 is a novel pro-fibrotic factor in renal fibrosis progression, for which TNFSF14 up-regulates Sphk1 expression." (PMID 33231567, 2020). "Inhibition of the TNFSF14 pathway is plausible for the clinical treatment of patients with renal fibrosis." (PMID 33231567, 2020). "However, Tnfsf14 deficiency markedly down-regulated UUO-induced inflammatory responses and renal fibrosis, which indicating that the protection observed in Tnfsf14 deficient mice, at least partially, is associated to the reduced immune-inflammatory response." (PMID 33231567, 2020). "However, how TNFSF14 pathway correlates Sphk1 expression during renal fibrosis progression is unclear." (PMID 33231567, 2020). "That may be the reason why fewer myofibroblasts and then the decreased renal fibrosis were observed in UUO-induced Tnfsf14 KO mice." (PMID 33231567, 2020). "However, the role of TNFSF14 in renal fibrosis pathogenesis remains unknown." (PMID 33231567, 2020). "In the present study, we found that the expression of TNFSF14 and its receptors HVEM and LTβR were rapidly up-regulated in UUO-induced mouse renal fibrosis model and in patients with fibrosis nephropathy." (PMID 33231567, 2020). "To address TNFSF14 relevance in determining kidney fibrosis, we used the unilateral ureteral obstruction (UUO)-induced renal fibrosis mouse model." (PMID 33231567, 2020). "However, no studies had evaluated the role of TNFSF14 in renal fibrosis development." (PMID 33231567, 2020).
steatosis (4 papers, 2020 to 2024). Increased lipid within the cytoplasm of cells. "However, it should be noted that one study highlighted that TNFSF14 deficiency in mice restored glucose homeostasis and reduced hepatic inflammation and steatosis." (PMID 34638990, 2021). "Steatosis in livers from WT, Tnfsf14−/−, Rag−/−, and DKO mice fed ND or HFD were evaluated using microscopy (Hematoxylin/Eosin staining)." (PMID 38255789, 2024). "NKT cells induced steatosis primarily by secreting TNF superfamily member 14 (TNFSF14), also known as lymphotoxin β receptor ligand (LIGHT), which increases FA uptake in hepatocytes, and NKT cells and CD8+ T cells cooperatively induced liver damage." (PMID 32443737, 2020). "NKT cells are able to secrete TNF superfamily member 14 (TNFSF14), which increases FFA uptake in hepatocytes and induces steatosis." (PMID 37361533, 2023).
Stroke (4 papers, 2023 to 2025). Sudden impairment of blood flow to a part of the brain due to occlusion or rupture of an artery to the brain. "In analysis of validation, tumor necrosis factor superfamily 14 (TNFSF-14) was a solitary biomarker having statistically significant downregulation in patients with post-stroke epilepsy compared with control group." (PMID 39847089, 2025). "In a recent prospective multicenter study, involving 894 patients with stable CAD, elevated levels of TNFSF14 were independently associated with adverse CV outcomes (composite of CV death, nonfatal MI, and stroke)." (PMID 36676179, 2023). "Twenty proteins were associated with outcome in univariable models after correction for multiple testing (FDR < 0.05), and for 5 the association was independent of clinical variables, including stroke severity (TNFSF14 [LIGHT], OSM, SIRT2, STAMBP, and 4E-BP1)." (PMID 37794467, 2023).
Arthritis (3 papers, 2017 to 2024). Inflammation of a joint. "TNFSF members, like RANKL, TNFSF13b and TNFSF14, etc., regulate differentiation, maturation and activation of osteoclastogenic cells in the development of osteoporosis caused by estrogen loss, arthritis or bone metastasis." (PMID 31627291, 2019).
atrial fibrillation (3 papers, 2023 to 2026). A disorder characterized by an electrocardiographic finding of a supraventricular arrhythmia characterized by the replacement of consistent P waves by rapid oscillations or fibrillatory waves that vary in size, shape and timing and are accompanied by an irregular ventricular response. "In conclusion, the TNFSF14/LIGHT–PI3Kγ–SGK1 axis is not only an important mediator of the transition from chronic inflammation to fibrosis in the heart, but also provides a potential therapeutic target for atrial remodeling during the progression of atrial fibrillation." (PMID 41561130, 2025).
fibrosis (3 papers, 2013 to 2023). the formation of excess fibrous connective tissue in an organ or tissue in a reparative or reactive process. "Tumor necrosis factor superfamily 14 (TNFSF14; also known as LIGHT) is highly expressed in the context of fibrosis and promotes disease progression in patients with fibrotic diseases such as pulmonary and skin fibrosis." (PMID 33654222, 2021). "Tumour necrosis factor superfamily protein 14 (TNFSF14), also called LIGHT, is an important regulator of immunological and fibrosis diseases." (PMID 37580750, 2023).
heart failure (3 papers, 2011 to 2025). Inability of the heart to pump blood at an adequate rate to meet tissue metabolic requirements. "Trans-fat feeding deregulated other stress-associated genes in males including phospholipase C δ1, the main cardiac isoform implicated in oxidative stress-induced REDOX signaling, and LIGHT/Tnfsf14, demonstrated to be upregulated in clinical and experimental heart failure." (PMID 22078008, 2011).
Hepatitis (3 papers, 2019 to 2023). Inflammation of the liver. "In agreement with previous results from the concanavalin A-induced hepatitis model, the morbidly obese subjects and the diabetic patients, circulating TNFSF14 concentrations were significantly increased in fibrotic nephropathy patients." (PMID 33231567, 2020).
Hyperglycaemia (3 papers, 2016 to 2023). "BMI correlated inversely with changes of PD-L1 and CD40 during hyperinsulinemia, Oncostatin-M, TNFSF14, FGF-21 and 4EBP-1 during hypoglycemia and CCL23, VEGF-A and CDCP1 during hyperglycemia (Rho ≤ -0.50)." (PMID 37400734, 2023).
Hypertension (3 papers, 2015 to 2020). The presence of chronic increased pressure in the systemic arterial system. "Clinical studies have shown an association between hypertension and the circulating levels of fibroblast growth factor 21 (FGF21), tumour necrosis factor superfamily member 14 (TNFSF14) and tumour necrosis factor-α (TNF-α)." (PMID 32858953, 2020). "It was subsequently shown in mouse models that the administration of TNFSF14 could induce hypertension." (PMID 32858953, 2020).
metabolic syndrome (3 papers, 2021 to 2022). A cluster of metabolic risk factors for CARDIOVASCULAR DISEASES and TYPE 2 DIABETES MELLITUS. "In conclusion, we have identified six novel TNFSF14 derived peptides and tested them in an in vitro and in vivo setting as therapeutics for the metabolic syndrome." (PMID 34638990, 2021). "In our current study, we sought to identify TNFSF14 derived peptides with therapeutic potential for the treatment of the metabolic syndrome." (PMID 34638990, 2021). "Our group has previously reported that TNFSF14 ablation exacerbates parameters of the metabolic syndrome under high fat feeding conditions, suggesting that TNFSF14 promotes metabolic benefits." (PMID 34638990, 2021). "We have successfully synthesized six novel TNFSF14 peptides and tested them in both in vitro and in vivo settings in an effort to assess their effects on the metabolic syndrome." (PMID 34638990, 2021). "In summary, we have successfully synthesized six new TNFSF14 peptides and tested their effect on the metabolic syndrome in a high fat diet mouse model." (PMID 34638990, 2021). "The role of TNFSF14 in the metabolic syndrome was controversial initially." (PMID 34638990, 2021). "However, the exact role that TNFSF14 plays in the metabolic syndrome is unknown." (PMID 34638990, 2021).
pancreatic ductal adenocarcinoma (3 papers, 2021 to 2024). An infiltrating adenocarcinoma that arises from the epithelial cells of the pancreas. "A previous study showed that adipose-derived stem cells pre-loaded with TNFSF14-expressing myxoma virus mediate improved tumor regression in pancreatic ductal adenocarcinoma." (PMID 37024802, 2023).
T lymphoma (3 papers, 2017 to 2021). "The expression of the LTβR in BECs and its ligands Ltα, Ltβ, and Tnfsf14 (LIGHT) in DCs remained unchanged in lymphoma." (PMID 34706240, 2021).
Allergy (2 papers, 2015 to 2025). An allergy is an immune response or reaction to substances that are usually not harmful. "Levels of tumor necrosis factor ligand superfamily member 14 (TNFSF14) and protein S100-A12 (EN-RAGE) increased over visits in both allergy groups." (PMID 40929127, 2025).
clear cell renal cell carcinoma (2 papers, 2022 to 2026). "In clear cell renal cell carcinoma, TNFSF14 was highly expressed in the high-TMB group, and the copy number of TNFSF14 was significantly correlated with classical immunocyte infiltration." (PMID 35445008, 2022).
hepatocellular carcinoma (2 papers, 2023 to 2024). A malignant tumor that arises from hepatocytes. "The expression of TNFSF14 in hepatocellular carcinoma (HCC) and other tumor tissues is significantly lower, and the HCC patients with low expression of TNFSF14 have high malignancy degree and poor prognosis." (PMID 38757752, 2024). "Therefore, we speculated that FNDC4 might play an inhibitory role in hepatocellular carcinoma by affecting the expression activity of some inflammatory cytokines, such as CD40, TNFSF14 or CXCL2." (PMID 38021165, 2023).
lung carcinoma (2 papers, 2021 to 2022). "The normalization of tumor vessels can be induced by TNFSF14, which subsequently inhibits the metastasis of melanoma and lung cancer." (PMID 34367975, 2021).
lupus (2 papers, 2017 to 2024). "TWEAK, the ligand of TNFRSF12A, has previously been reported to be involved in lupus pathology, and LIGHT (TNFSF14), a ligand of HVEM (TNFRSF14), is commonly dysregulated in murine lupus." (PMID 39688922, 2024).
Myocardial fibrosis (2 papers, 2023 to 2025). "Tumor necrosis factor superfamily member 14 (TNFSF14, also known as LIGHT) contributes to myocardial fibrosis by influencing the phenotype of cardiac fibroblasts through M2 macrophage polarization." (PMID 40895433, 2025).
nephritis (2 papers, 2024 to 2025). Inflammation of renal tissue. "Tfh cells were found to regulate B-cell differentiation via CD40-CD40L; in renal tissue of nephritis, results indicate that Tfh cells (CD4+ICOS+) and B cells directly interact in situ in the glomerulus, with intensified signaling through LTA/TNFSF14 (LIGHT)-TNFRSF14." (PMID 40001494, 2025).
non-small cell lung carcinoma (2 papers, 2021 to 2023). A group of at least three distinct histological types of lung cancer, including non-small cell squamous cell carcinoma, adenocarcinoma, and large cell carcinoma. "LIGHT/TNFSF14 could promote osteolytic bone metastases in non-small cell lung cancer patients." (PMID 38012562, 2023).
sarcoma (2 papers, 2023 to 2024). A usually aggressive malignant neoplasm of the soft tissue or bone. "To determine the functional role of TNFSF14 in sarcoma, we overexpress TNFSF14 in SW872 and HT1080 cells with the overexpression plasmid vector." (PMID 38720884, 2024). "Cytological experiments showed that soft tissue sarcoma cell lines overexpressing TNFSF14 could inhibit the proliferation and migration of sarcoma cells." (PMID 38720884, 2024). "Interestingly, DC.Tbet cells already secreted CCL19, CCL21, LIGHT/TNFSF14, and lymphotoxin, thereby inducing TLS formation even in lymphotoxin-deficient mice transplanted with MCA205 sarcoma cells and treated with DC.Tbet cells." (PMID 38111571, 2023).
viral pneumonia (2 papers, 2026). Inflammation of the lung parenchyma that is caused by a viral infection. "Blocking TNFSF14 or the LTβR during severe viral pneumonia is intriguing as a potential therapeutic approach." (PMID 41542776, 2026). "Along with evidence of roles for TNFSF14 and LTβR in safeguarding AMs, there is enthusiasm for further considering TNFSF14 or LTβR blockade in viral pneumonias." (PMID 41542776, 2026).
bacterial pneumonia (1 paper, 2026). Acute infection of the lung parenchyma caused by bacteria (e.g., Streptococcus pneumoniae, Haemophilus influenzae, Chlamydia pneumoniae, Mycoplasma pneumoniae, and Legionella pneumophila). "Targeting the TNFSF14-mediated intercellular communication network in the virus-infected lung can, therefore, improve host defense, minimizing the risk of subsequent bacterial pneumonia and ameliorating the disease outcome." (PMID 41252214, 2026). "On the basis of these results, we conclude that targeting the TNFSF14 signaling axis could revert TR-AM death in the aftermath of severe IAV-induced lung injury and thus prevent the transition to secondary bacterial pneumonia." (PMID 41252214, 2026).
chordoma (1 paper, 2023). Chordomas are rare malignant tumors arising from embryonic remnants of the notochord in axial skeleton. "The expression of AMOT, RYR3, P2RX5, and TNFSF14 were higher in recurrent chordomas than primary chordomas while NPTX1 was contrast." (PMID 38012562, 2023). "miR-186-5p, miR-125b-5p, miR-1260a, and their target protein mRNAs including AMOT, NPTX1, RYR3, P2RX5, TNFSF14 may be the basement of chordoma research." (PMID 38012562, 2023).
chronic heart failure (1 paper, 2023). "TNFSF14/LIGHT is produced mainly by activated T cells and myeloid cells and is increased in the plasma of patients with acute ischemic stroke and participates in the progression of chronic heart failure." (PMID 36851766, 2023).
dental caries (1 paper, 2024). The decay of a tooth, in which it becomes softened, discolored, and/or porous. "TNFSF14 may be involved in developing biomaterials intended to enhance pulpal healing and reduce inflammatory responses, thereby providing an innovative strategy for addressing dental caries and its associated consequences." (PMID 39727964, 2024). "Dental caries remains a significant worldwide health issue; introduction of TNFSF14 as an alternative therapeutic agent could transform the management of carious lesions associated with pulpal inflammation." (PMID 39727964, 2024).
dental pulp disease (1 paper, 2024). "Conducting experiments on other pulpal cell types, as well as using other inducers of inflammation, such as lipopolysaccharides, will add to our understanding of the role of TNFSF14 in dental pulp disease." (PMID 39727964, 2024).
endothelial dysfunction (1 paper, 2022). In vascular diseases, endothelial dysfunction is a systemic pathological state of the endothelium (the inner lining of blood vessels) and can be broadly defined as an imbalance between vasodilating and vasoconstricting substances produced by (or acting on) the endothelium. "OSM, MCP‐2, TGF‐α, and CXCL6 are likely to have an association with endothelial dysfunction and some are mostly or additionally involved in IR (MCP‐1, FGF‐21, TRAIL, and ADA) or insulin metabolism (TNFSF14/LIGHT)." (PMID 36467791, 2022).
Erythema (1 paper, 2025). Redness of the skin, caused by hyperemia of the capillaries in the lower layers of the skin. "Consistent with these recently published data, our study further confirmed that TNFSF14 is required for IMQ‐induced skin inflammation evidenced by significantly reduced epidermal thickening, scaling, and erythema in TNFSF14 knockout mice." (PMID 40768619, 2025).
Hyperkeratosis (1 paper, 2025). Hyperkeratosis is a histopathological term defining a thickened stratum corneum and may be present in many different skin conditions, with many possible overlaps. "Correspondingly, blocking TNFSF14 signalling remarkably alleviated hyperkeratosis and thickening of the epidermal layer." (PMID 40768619, 2025).
inflammatory skin disorders (1 paper, 2025). "Taken together, these data suggest that TNFSF14 is critical for KC dysfunction in inflammatory skin disorders, including PS." (PMID 40768619, 2025).
Lipedema (1 paper, 2022). Disorder of adipose tissue characterized by symmetric and bilateral enlargement of the lower extremities due to abnormal deposition of subcutaneous fat often in obese women. "Further studies are needed to understand whether the most different inflammatory markers between these groups (TNFSF14, CASP8, EN-RAGE, EIF4EBP1, ADA, MCP-1) play a mechanistic role in lipedema development and perpetuation." (PMID 36387874, 2022).
lung adenocarcinoma (1 paper, 2022). A carcinoma that arises from the lung and is characterized by the presence of malignant glandular epithelial cells. "The staining intensity of TNFSF14, JAM2, HGF, SPN, and LIFR in the tumors of 50 lung adenocarcinoma patients was first analyzed by immunohistochemistry and quantified according to H-scores." (PMID 36072807, 2022).
migraine (1 paper, 2008). "Further studies need to be performed with TNFSF7 and MO affected individuals and also other possible TNF receptor family homologues on C19p13, such as TNFSF9 (C19p13.3) and TNFSF14 (C19p13.3) should be tested for migraine involvement." (PMID 19018300, 2008).
non-alcoholic steatohepatitis (1 paper, 2023). "Specifically, TNFSF14 and GAD1 are highly expressed in HCC; STARD1 promotes the progression of non-alcoholic steatohepatitis to HCC via bile acids; DHRS4-AS1 ameliorates HCC by suppressing proliferation and promoting apoptosis via the miR-522-3p/SOCS5 axis." (PMID 36899918, 2023).
osteomyelitis (1 paper, 2025). An acute or chronic inflammation of the bone and its structures due to infection with pyogenic bacteria. "We next investigated the clinical significance of PCD pathways by correlating their GSVA scores with representative inflammatory biomarkers of osteomyelitis, including IL6R, MMP8, TNFRSF11A, IL17RB, TNFSF14, and TGFBR1." (PMID 41050653, 2025).
ovarian carcinoma (1 paper, 2017). A malignant neoplasm originating from the surface ovarian epithelium. "We identified TNFSF14 as a potential biomarker for serous ovarian cancer due to its significantly higher levels in late stage ovarian cancer compared to its levels in serum samples from the other three groups we examined." (PMID 29051715, 2017). "Three of these proteins, CXCL13, FADD, and TNFSF14 have not been reported in the literature as having an association with ovarian cancer, and may serve as novel candidate biomarkers for ovarian cancer." (PMID 29051715, 2017). "Notably, CXCL13, TNFSF14, and FADD had not been previously identified in ovarian cancer tissues or serum." (PMID 29051715, 2017).
ovarian serous cystadenocarcinoma (1 paper, 2023). A malignant serous cystic epithelial neoplasm arising from the ovary. "TNFSF14 is positively correlated with GSDMB in KIRC (rho = 0.459, p < 0.0001), SKCM (rho = 0.307, p < 0.0001), and ovarian serous cystadenocarcinoma (OV) (rho = 0.251, p < 0.0001) patients." (PMID 37064151, 2023).
Psoriasiform dermatitis (1 paper, 2025). A skin abnormality characterized by redness and irritation, with thick, red skin that displays flaky, silver-white patches (scales). "Overall, the TNFSF14 knockout attenuated keratinisation and apoptosis in mice with IMQ‐induced psoriasiform dermatitis." (PMID 40768619, 2025).